GLDC (glycine decarboxylase)
Diseases named in the same sentence as GLDC in open-access papers (continued):
Sharing a sentence is not in itself a finding about the gene and the disease.
neuroblastoma (7 papers, 2020 to 2025). Neuroblastoma (NB) is the most common solid, extracranial childhood tumor. "GLDC knockdown mitigates cell proliferation and tumorigenicity via causing G1 arrest in MYCN-amplified neuroblastoma cells." (PMID 36275705, 2022). "A report has shown that the expression of GLDC is significantly increased in MYCN amplified neuroblastoma tumors and cell lines, and GLDC plays a key role in maintaining the proliferation of neuroblastoma cells." (PMID 36275705, 2022). "GLDC expression is markedly increased in MYCN-amplified neuroblastomas, which is required for neuroblastoma cell proliferation and tumorigenicity." (PMID 34244482, 2021). "GLDC contributes to metabolic reprogramming exclusively in MYCN-amplified neuroblastoma cells, as demonstrated by the effect of GLDC knockdown on central carbon metabolism pathways, including glycolysis and the TCA cycle, as well as lipid synthesis." (PMID 32547946, 2020). "N-Myc activates GLDC transcription and is essential for maintaining high levels of GLDC expression in MYCN-amplified neuroblastoma cells, suggesting that GLDC and other SGOC pathway genes are cooperatively upregulated." (PMID 32547946, 2020). "The high expression of GLDC plays a key role in the proliferation of neuroblastoma cells." (PMID 37781511, 2023). "High GLDC expression in neuroblastoma cells prevents the accumulation of toxic metabolites." (PMID 35873461, 2022). "As a result, GLDC knockdown markedly inhibits the proliferation and tumorigenicity of MYCN-amplified neuroblastoma cell lines." (PMID 36077650, 2022).
gastric cancer (4 papers, 2020 to 2025). A primary or metastatic malignant neoplasm involving the stomach. "In gastric cancer, GLDC acts as a tumor suppressor gene, and the hypermethylation of its promoter makes it silent at the transcriptional level and promotes the occurrence of gastric cancer." (PMID 36770809, 2023).
glioblastoma (4 papers, 2018 to 2024). The most malignant astrocytic tumor (WHO grade IV). "In contrast, GLDC inhibition in glioblastoma causes an accumulation of glycine and results in reduced cell viability, indicating that glycine catabolism by GLDC is critical for proliferation and tumorigenesis." (PMID 35873461, 2022). "The main enzyme in the glycine cleavage pathway, GLDC, is upregulated in lung-tumor initiating cells as well as glioblastomas, and sustained GLDC hyperactivity has been shown to be critical for tumorigenesis." (PMID 30159313, 2018). "Moreover, SHMT2 and GLDC have been shown to antagonize the activity of PKM2 and reduce oxygen consumption in glioblastoma multiforme (GBM), thereby driving a survival advantage by reprogramming the metabolic state of the tumor." (PMID 39239102, 2024).
melanoma (4 papers, 2019 to 2024). A malignant, usually aggressive tumor composed of atypical, neoplastic melanocytes. "Another study showed that a high expression of glycine decarboxylase protein in primary melanoma was closely linked to early metastasis in patients." (PMID 38136676, 2023). "In conclusion, our iPSC-based study reveals a significant association of NC marker GLDC protein expression with melanoma prognosis." (PMID 30641895, 2019). "In addition, our results show that a greater expression of the GLDC protein (IHC score > 9.33) in primary melanoma increases the risk for early metastasis." (PMID 30641895, 2019). "In addition, GLDC upregulation in primary melanoma correlates with a risk for early metastasis." (PMID 30641895, 2019). "Malignant melanoma patients with tumor samples with an IHC score > 8 for Anti-CD271, >8 for Anti-GLDC, and >9 for Anti-ERRFI1 are more likely to die early and therefore show a poorer prognosis after diagnosis stage IV in comparison with patients with smaller IHC scores for the described antibodies." (PMID 30641895, 2019). "According to our study, antibodies against CD271, GLDC, and ERRFI1 could be used as a tool to predict prognosis of overall survival at stage IV disease of malignant melanoma." (PMID 30641895, 2019).
periodontitis (4 papers, 2016 to 2024). An acute or chronic inflammatory process that affects the tissues that surround and support the teeth. "Out of the 20 most upregulated genes in periodontitis tissues compared to controls, five were induced in DAC-treated GFs in our experiments (CSF3, GLDC, SAA1, SAA2, GDF15), highlighting the notion that DNMT inhibitors upregulate several genes that are associated with periodontitis pathology." (PMID 36776856, 2023).
renal carcinoma (4 papers, 2020 to 2025). A carcinoma arising from the epithelium of the renal parenchyma or the renal pelvis. "In conclusion, the experimental results showed that over expression of SUCLG1, PCK2, and GLDC can inhibit the progression of renal cancer cells." (PMID 32699530, 2020). "In order to clarify the mechanisms of SUCLG1, PCK2, and GLDC in renal cancer, this study further focused on their proliferation, migration, invasion, and cell cycle of renal cancer cells through cell biology experiments." (PMID 32699530, 2020). "In this study, we analyzed the databases of GEO, TCGA, GEPIA, Oncomine, and found that six genes (SUCLG1, PCK2, GLDC, SLC12A1, ATP1A1, and PDHA1), are related to the survival prognosis of patients with renal cancer." (PMID 32699530, 2020). "In order to clarify the molecular mechanism of these genes, we selected 3 molecules (SUCLG1, PCK2, GLDC) that have not previously been studied in renal cancer, and conducted in vitro experiments on them." (PMID 32699530, 2020).
liver cancer (3 papers, 2018 to 2022). An epithelial or non-epithelial malignant neoplasm that arises from the liver. "On the other hand, GLDC knockdown suppresses Huh-7 liver cancer and A549 LUAD cell growth." (PMID 29911072, 2018). "GLDC upregulation induces autophagy in HCC cells and inhibits liver cancer metastasis." (PMID 35873461, 2022).
ovarian carcinoma (3 papers, 2014 to 2023). A malignant neoplasm originating from the surface ovarian epithelium. "GLDC mRNA expression is low in normal ovarian and fallopian tube samples, but it is detected at high protein levels in ovarian cancer." (PMID 37923835, 2023). "After consulting the public database DepMap Public 22Q4 at Cancer Cell Line Encyclopedia (CCLE), we identified the ovarian cancer cell lines with higher GLDC expression based on average [log2(TPM + 1)] expression." (PMID 37923835, 2023). "We further explored the possible impact of GLDC expression on the response of ovarian cancer cells to chemotherapy." (PMID 37923835, 2023). "Combined treatment with GLDC inhibitors and platinum-based compounds, a completely novel strategy, might enhance sensitivity to chemotherapy in ovarian cancer." (PMID 37923835, 2023). "We then measured GLDC mRNA expression in IGROV1 and other ovarian cancer cell lines and in the HIO 180 non-transformed epithelial ovarian cancer cells to confirm that IGROV1 had the highest GLDC expression among them." (PMID 37923835, 2023).
prostate carcinoma (3 papers, 2019 to 2023). A carcinoma that arises from epithelial cells of the prostate gland. "LDHA has been identified as contributing to glycolysis in tumors, which strengthens the evidence that GLDC promotes glycolysis in prostate cancer." (PMID 37781511, 2023). "Glycine decarboxylase (GLDC) is one of the core enzymes for glycine metabolism, and its biological roles in prostate cancer (PCa) are unclear." (PMID 37781511, 2023). "Herein, we aimed to explore the core role of GLDC in glycolytic metabolism and its biological function in promoting the invasion, metastasis and immune escape of prostate cancer." (PMID 37781511, 2023). "Our research confirmed that GLDC promoted the invasion and metastasis of prostate cancer in in vivo and in vitro experiments and significantly affected the survival of PCa patients." (PMID 37781511, 2023). "Surprisingly, we found that GLDC correlates well with LDHA in gene and protein expression and regulates lactate levels through LDHA, strengthening the evidence that GLDC promotes glycolysis in prostate cancer." (PMID 37781511, 2023). "This evidence indicates that GLDC plays crucial roles in glycolytic metabolism, invasion and metastasis, and immune escape in PCa, and it is a potential therapeutic target for prostate cancer." (PMID 37781511, 2023). "Heatmap analysis showed the differences in metabolites in different GLDC expression groups of prostate cancer cell lines." (PMID 37781511, 2023). "First, we analyzed the expression of GLDC in 51 normal and 489 prostate cancer patients from the TCGA database, which showed that GLDC mRNA levels were obviously higher in prostate cancer samples than in normal prostate tissues." (PMID 37781511, 2023). "This evidence suggested that GLDC significantly affects the prognosis of prostate cancer patients." (PMID 37781511, 2023). "In addition, GLDC was significantly upregulated in the lymph node metastasis group (N1) when compared with the primary group (N0) of prostate cancer according to TCGA patients." (PMID 37781511, 2023). "This evidence indicated the key role of GLDC in promoting glycolysis in prostate cancer." (PMID 37781511, 2023). "Moreover, we found that GLDC correlated well with HIF-1α in gene expression 425 in TCGA prostate cancer patients." (PMID 37781511, 2023). "This evidence suggested that GLDC might affect immune cell infiltration or tumor immune escape by mediating tumor glycolysis, and its roles in prostate cancer need to be further confirmed." (PMID 37781511, 2023). "This evidence suggested the critical role of GLDC in immune escape in prostate cancer." (PMID 37781511, 2023). "Furthermore, we confirmed that GLDC was highly expressed in prostate cancer, especially in metastatic prostate cancer, both in tissues (tumors with M1) and cell lines (DU145, LNcap)." (PMID 37781511, 2023). "Studies have shown that GLDC is upregulated in lung, brain, and prostate cancers." (PMID 30804330, 2019). "However, the biological functions of GLDC in prostate cancer have rarely been revealed." (PMID 37781511, 2023). "Inhibition of GLDC transcript represses cell proliferation and colony formation in NSCLC and prostate cancer cells." (PMID 36275705, 2022). "Our study showed a significant negative correlation between GLDC and functional immune cell infiltration (CD8+ T cells, NK cells, B cells, etc.)but a positive correlation with immunosuppressive cells (Treg cells, etc.), which might be another reason for the poor prognosis of GLDC in prostate cancer." (PMID 37781511, 2023).
epilepsy (2 papers, 2020 to 2024). A brain disorder characterized by episodes of abnormally increased neuronal discharge resulting in transient episodes of sensory or motor neurological dysfunction, or psychic dysfunction. "Mutation of GLDC or AMT causes non‐ketotic hyperglycinemia (NKH), a severe life‐limiting autosomal recessive neurometabolic disorder characterised by accumulation of excess glycine in body fluids and tissue, epilepsy and profound developmental delay." (PMID 32743799, 2020).
influenza (2 papers, 2019 to 2025). An acute viral infection of the respiratory tract, occurring in isolated cases, in epidemics, or in pandemics; it is caused by serologically different strains of viruses (influenzaviruses) designated A, B, and C, has a 3-day incubation period, and usually lasts for 3 to 10 days. "Glycine decarboxylase (GLDC) was prioritized as a candidate susceptibility gene to severe influenza in humans." (PMID 30498026, 2019). "To substantiate GLDC as a functional susceptibility gene to severe influenza, we extensively searched for the possible mechanism(s)." (PMID 30498026, 2019). "Under this line of reasoning, GLDC was prioritized as a candidate susceptibility gene to severe influenza, which prompted us to conduct in vitro and mouse studies and validated GLDC as a functional susceptibility gene to severe influenza." (PMID 30498026, 2019). "GLDC was prioritized as a potential susceptibility gene to severe influenza through an integrative approach." (PMID 30498026, 2019). "We performed a series of in vitro and in vivo experiments and established GLDC as a functional susceptibility gene to severe influenza." (PMID 30498026, 2019). "In this study, we have utilized integrative approaches to identify and characterize GLDC as an important susceptibility gene to severe influenza." (PMID 30498026, 2019). "GLDC is a functional susceptibility gene to severe influenza in humans." (PMID 30498026, 2019). "Conceivably, the differential GLDC expression encoded by genetic variation, probably with a modest effect, could be magnified in the virus‐infected individuals and substantially affect the susceptibility to severe influenza." (PMID 30498026, 2019).
ketotic hyperglycinemia (2 papers, 2020). "Mutation of the GCS component glycine decarboxylase (GLDC) in non‐ketotic hyperglycinemia (NKH) causes accumulation of glycine in body fluids, but there is a gap in our knowledge regarding the effects on glycine metabolism in tissues." (PMID 32743799, 2020). "Ventriculomegaly and hydrocephalus are associated with loss of function of glycine decarboxylase (Gldc) in mice and in humans suffering from non-ketotic hyperglycinemia (NKH), a neurometabolic disorder characterized by accumulation of excess glycine." (PMID 31794432, 2020).
lymph node metastasis (2 papers, 2019 to 2023). "Downregulation of GLDC was associated with tumor shape, lymph node metastasis, BCLC stage, and TNM stage." (PMID 30804330, 2019).
neural tube defect (2 papers, 2018 to 2022). A congenital defect characterized by failure of the neural tube to close completely; this results in the presence of openings in the brain or spinal cord. "In a study population of patients from the UK, Sweden and Japan, two of the genes encoding GCS enzymes, AMT and GLDC, were found to have missense variants associated with neural tube defects (NTDs)." (PMID 29988937, 2018). "Additionally, GLDC/Gldc has been linked to neural tube defects (NTDs) in humans and mice, further implicating its role in development." (PMID 36551976, 2022).
Obesity (2 papers, 2019 to 2021). Accumulation of substantial excess body fat. "We report here that GLDC is over‐expressed in animal models of diabetes, obesity, and nutritional stress, and that GLDC gene expression is strongly regulated by metabolic hormones, especially glucagon." (PMID 34342168, 2021). "The findings reported here indicate that GLDC expression is strongly regulated by metabolic hormones and is indeed over‐expressed in animal models of diabetes and obesity." (PMID 34342168, 2021). "The findings presented above clearly show that hepatic GLDC gene expression is altered in a variety of physiologic states including nutritional stress (fasting) and metabolic stress (diabetes and obesity)." (PMID 34342168, 2021). "The findings presented here show that hepatic GLDC gene expression is elevated in mouse models of obesity and diabetes, as well as by fasting." (PMID 34342168, 2021). "Together these findings indicate that GLDC expression is elevated in the states of metabolic stress such as diabetes and obesity." (PMID 34342168, 2021). "Taken together, our results suggest that elevated GLDC expression contributes to the reduced levels of circulating glycine seen in obesity and diabetes." (PMID 34342168, 2021). "In summary, our findings indicate that the expression of the glycine degrading enzyme GLDC is elevated by metabolic stress related to diabetes and suggest that the reduced levels of glycine seen in diabetes and obesity are due at least in part to elevated GLDC expression." (PMID 34342168, 2021). "To determine whether GLDC expression was similarly elevated in diet‐induced obesity, we examined hepatic GLDC protein levels in C57BL6/J mice fed either a low‐fat (10% calories from fat) or a high‐fat (45% calories from fat) diet for 16 weeks." (PMID 34342168, 2021).
osteosarcoma (2 papers, 2022). A usually aggressive malignant bone-forming mesenchymal neoplasm, predominantly affecting adolescents and young adults. "In the TARGET‐osteosarcoma dataset, the GLDC mRNA level was negatively associated with the prognosis of patients with osteosarcoma, indicating that rs55933544 may influence prognosis by regulating IL33 and/or GLDC." (PMID 36305631, 2022). "Genetic variants in ABCC3, ABCC5, FasL, GLDC and GSTP1 were repeatedly associated to osteosarcoma treatment outcome, using very heterogeneous efficacy outcomes." (PMID 36536332, 2022).
phyllodes tumor (2 papers, 2018 to 2023). A benign, borderline, or malignant fibroepithelial neoplasm arising from the breast and rarely the prostate gland. "Moreover, the expression level of GLDC is associated with higher mortality and lower survival rates in cancer patients, such as thyroid cancer and phyllodes tumor 17,18." (PMID 37781511, 2023). "The expression of serine–glycine biosynthetic genes including PHGDH, PSAT1 and GLDC is correlated to tumor grade and shorter disease-free survival in patients with phyllodes tumor." (PMID 29911072, 2018).
viral infection (2 papers, 2019 to 2025). "To test this reasoning, we stimulated cells with polyinosinic-polycytidylic acid [poly(I:C)], a dsRNA analog that mimics viral infection and found poly(I:C) markedly increased interferon α (IFNα) in GLDC deficient cells compared with that in control cells." (PMID 39781465, 2025). "GLDC inhibition and depletion significantly amplified antiviral response of type I IFNs and ISGs upon viral infection and suppressed the replication of H1N1 and H7N9 viruses." (PMID 30498026, 2019). "Glycine decarboxylase (GLDC) modulates host antiviral response upon viral infection due to the existence of GLDC‐pyrimidine biosynthesis‐innate immunity axis." (PMID 30498026, 2019). "We demonstrated that GLDC overexpression significantly promoted the replication of MERS‐CoV at 48 hpi, indicating that GLDC‐orchestrated viral growth was operational in other viral infections." (PMID 30498026, 2019). "Given the previous result that GLDC plays a crucial role in viral infection 31, we reasoned that GLDC-ISGF3-ISG axis could be induced by viral infection." (PMID 39781465, 2025). "Since GLDC affected growth of influenza viruses via modulating antiviral response, we tested whether this is operational in other viral infections." (PMID 30498026, 2019). "In addition, the axis may be functional in other viral infections since GLDC overexpression also significantly enhanced the replication of MERS‐CoV." (PMID 30498026, 2019).
anencephaly (1 paper, 2018). A rare neural tube defect during pregnancy, resulting in the absence of a large portion of the brain and skull in the fetus. "In addition, we have identified 4 more patients (1 craniorachischisis and 3 anencephaly) carrying rare GLDC variants predicted to be damaging." (PMID 29205322, 2018).
colorectal cancer (1 paper, 2024). A primary or metastatic malignant neoplasm that affects the colon or rectum. "Glycine, as a source of one-carbon units, together with increased expression of glycine decarboxylase, promotes the growth of cancer cells, e.g., for colorectal cancer." (PMID 38731854, 2024).
developmental delays (1 paper, 2022). "Mutations in GLDC account for about 75% of NKH cases, causing a wide variety of symptoms including seizures and developmental delays." (PMID 36551976, 2022).